SOX9 (SRY-box transcription factor 9)
Diseases named in the same sentence as SOX9 in open-access papers (continued):
Sharing a sentence is not in itself a finding about the gene and the disease.
tumor (continued). "Furthermore, both MALAT1 and SOX9 expressions were associated with age, tumor size, and TNM stage, making these two genes potential candidates for prognosis tools." (PMID 32438606, 2020). "Notably, compared to H1299‐shSOX9 cells expressing WT SOX9, cells expressing the ubiquitination‐deficient SOX9 mutants (4KR or K249R) showed increased tumor growth in xenograft model." (PMID 33173725, 2020). "Furthermore, high levels of SOX9 have been associated with tumor grade, dismal prognosis and poor patient survival in patients of those types of cancer." (PMID 31941916, 2020). "SOX9 gene has been implicated in different types of cancer as an oncogene; however, it also may behave as a tumor suppressor." (PMID 31057614, 2019). "In addition, knockdown of SOX9 expression resulted in a loss of the TGF-β-mediated EMT phenotype in tumor cells." (PMID 29245941, 2017). "Additionally, the pooled odds ratios (ORs) indicated that SOX9 over-expression is associated with large tumor size, lymph node metastasis, distant metastasis and a higher clinical stage." (PMID 29348895, 2017). "In addition, low SOX9 expression was associated with decreased tumor growth and metastasis in the animal model." (PMID 26009899, 2015). "Sox9 is overexpressed in several tumor types and associated with poor survival." (PMID 25004243, 2014). "This suggested that Sox9 was a new hallmark of lung AC, in which Sox9 might contribute to the gain of tumor growth potential." (PMID 23443092, 2012). "Moreover, SOX9 hypermethylation was significantly associated with tumour grade and overall survival." (PMID 18087279, 2008). "Moreover, the significant association of SOX9 methylation with clinicopathological tumour grade and survival further supported their association with cancer progression." (PMID 18087279, 2008). "Additionally, SOX9 is strongly linked to tumor cells' poor prognosis." (PMID 41293317, 2025). "Besides, SOX9 has been shown to be closely associated with tumor immunity." (PMID 37020558, 2023). "Therefore, we suppose that SOX9 influences the development of karyotypic aberrations and the accumulation of genetic mutations in oncogenesis, thereby probably affecting the way and time of tumor development and progression." (PMID 33076370, 2020). "However, the exact mechanisms underlying SOX9 functions during tumor formation and development largely remain unclear until now." (PMID 32398735, 2020). "Loss of SOX9 expression might be more relevant in early-stage disease, which is difficult to assess in cell lines as they accumulate mutations and genomic alterations, hence being more close to advanced tumour stages." (PMID 31275454, 2019). "Therefore, aberrant expression of linc-ROR may serve as a novel mechanism underlying SOX9 deregulation, and the linc-ROR–miRNA–SOX9 regulatory network provides a novel vision to understand the oncogenic and tumor suppressor network puzzle." (PMID 29237490, 2017). "Within 24 h, fluorescence imaging showed markedly higher tumor accumulation of iRGD NPs@si‐SOX9/CL compared with NPs@si‐SOX9/CL." (PMID 41270217, 2026). "For example, SOX2 sustains tumor stemness to promote chemotherapy resistance, SOX4 modulates EMT and angiogenesis and SOX9 collaborates with EGFR/KRAS signaling pathways to drive tumor invasion." (PMID 41268614, 2026). "CRISPR/Cas9 offers permanent genomic editing of SOX loci, bypassing delivery instability by enabling knockout or base editing in preclinical patient-derived tumor xenograft models, where SOX9 ablation halts metastasis more durably than siRNA." (PMID 41268614, 2026). "Expression of SOX9/TIMP1/PI3K pathway components in tumor tissues was examined by immunohistochemistry and Western blotting." (PMID 41270217, 2026). "For instance, the immunoprofiles of most testicular SCSTs show substantial overlap, with purported ‘sex cord markers’ such as WT1, FOXL2 and SOX9 being expressed in tumours with seemingly pure stromal phenotype and vice‐versa." (PMID 41384702, 2026).
tumor (continued). "Mechanistically, PTEN deficiency induces activation of NOTCH and upregulation of transcriptional factor SOX9, which plays a central role in tumor cell transformation." (PMID 41646383, 2026). "Key members such as SOX2, SOX4 and SOX9 notably influence the malignant progression of NSCLC by regulating processes including tumor stemness, EMT, cell proliferation, apoptosis, invasion, metastasis and drug resistance." (PMID 41268614, 2026). "Tumor formation occurred in approximately 69% of recipients, with tumors exhibiting biphasic morphology and Sox9 expression." (PMID 40867318, 2025). "Immunofluorescence co‐localization experiments compared the co‐expression of SOX9 and p‐YAP1 (Ser351) in subcutaneous tumor tissues with SOX9 overexpression and SOX9‐KO and in human tissues between adjacent and cancerous tissues." (PMID 39523731, 2025). "High-definition Stereo-seq volumes show that these vessels articulate long, finger-like processes that penetrate deep into the viable tumour mass, guiding CXCL12-secreting cancer-associated fibroblasts and SOX9 + stem-like tumour cells into close proximity." (PMID 40740859, 2025). "This cluster was enriched in genes involved in differentiation and developmental processes (for example, SOX1 and SOX9, HOXD3 and HOXD8, and TBX4) and genes implicated as tumor suppressors (for example, SOX1 and SOX17, TSHZ3, WT1-AS, and FGF14)." (PMID 40931149, 2025). "Clusters 20 and 12 from the original UMAP (Figure A4b) were identified as PDAC tumor cells based on their expression of marker genes, including Sox9, Krt7, Krt19, or Epcam." (PMID 39857986, 2025). "Lower SOX2 and SOX9 expression levels are required in lymph node metastases while high‐expression levels provide an advantage in tumor recurrence." (PMID 39180200, 2025). "SOX9 is frequently overexpressed in various solid malignancies, where its expression levels positively correlate with tumor occurrence and progression." (PMID 41293317, 2025). "According to the mechanism by which SOX9 regulates various immune components, its mechanism of involvement in tumor immune escape is as follows." (PMID 41293317, 2025). "To strengthen the case for the functional role of Sox9 loss to increased SOX2 levels and tumor progression, we studied how Sox9 genetic inactivation affected the AKP model and the tumors arising (termed AKPS tumors)." (PMID 40179020, 2025). "This study utilized data mining and analysis from the TCGA and GTEx databases, revealing that SOX9 expression was significantly upregulated in multiple tumor tissues, including GBM, compared to adjacent normal tissues." (PMID 40692865, 2025). "Elevated SOX9 expression in tumor tissue promotes the transition of macrophages from the M1 to the M2 phenotype." (PMID 41293317, 2025). "On the other hand, it also displayed alterations in the expression of key genes, including SOX9, E2F family, KRAS, BCL2L1, and MYC, indicative of a predisposition for BC tumor initiation, stemness, and progression." (PMID 40801146, 2025). "Sox9 inactivation was notably correlated with the increased expression of SOX2, suggesting SOX9 inactivation plays a role in promoting tumor progression in part by SOX2 upregulation." (PMID 40179020, 2025). "Elevated SOX9 expression in tumors correlates with reduced T cell infiltration, facilitating tumor immune escape and progression." (PMID 41293317, 2025). "We designed a subcutaneous tumor model by knocking out SOX9 in CRC cells to further validate the molecular mechanisms of CMD‐BHQ3‐PTL/DOX@RBCm." (PMID 39523731, 2025). "Our findings from the mouse models recapitulate features seen in patients with CRC, where low SOX9 expression correlated with higher tumor grade, increased lymphatic invasion, and poorer patient survival." (PMID 40179020, 2025). "In our study patients with OSCC show lower levels of SOX2 and SOX9 in lymph node metastases while patients with tumor recurrence have significantly higher expression levels." (PMID 39180200, 2025).
tumor (continued). "In tumor-bearing mice, overexpression of SOX9 accelerates tumor growth, while inhibition of glycolysis reverses this effect and suppresses tumor progression." (PMID 40535811, 2025). "SOX9 also promotes uncontrolled proliferation and malignant properties in tumor cells by inhibiting INK4A/ARF expression through BMI-1 induction." (PMID 39907598, 2025). "Nevertheless, its correlation with tumor aggressiveness highlights SOX9 as a compelling, though complex, target for the development of more potent cancer therapies." (PMID 39907598, 2025). "For in tumor, numerous studies have demonstrated that SOX9 influences tumor resistance via multiple signaling pathways, including PI3K/AKT, Wnt/β-catenin, and TGFβ/Smad." (PMID 41293317, 2025). "The authors attributed gemcitabine resistance to SOX9 ability to stimulate some stem cell traits in tumor cells." (PMID 40141294, 2025). "We validated that Ntn1 cKO reduced the expression of Zeb1, Vim, and Sox9 in KPC tumor cells, using qRT-PCR of FACS-sorted tdtomato-labeled tumor cells from Rosa26-LSL-tdtomato; KPC or KPCN mice." (PMID 40777309, 2025). "Here, we utilized multiomics, tumor microarrays, and epigenetic modulation to demonstrate that SOX9 is a key chemo-induced driver of chemoresistance in HGSOC." (PMID 41031891, 2025). "Within tumor cells, SOX9 suppresses the activity, proliferation, and killing function of T cells and NK cells directly or indirectly through various mechanisms." (PMID 41293317, 2025). "The H‐Score of the primary tumor samples and the matched lymph node metastases differed significantly with lower scores in lymph node metastases for SOX9 (paired t test: p < 0.001)." (PMID 39180200, 2025). "The H‐Score of the primary tumor samples and the lymph node metastases differed significantly with lower scores in lymph node metastases for SOX9 (paired t test: p < 0.001)." (PMID 39180200, 2025). "Specifically, patients with vascular or perineural invasion, poor tumor differentiation, larger tumor size, or lymph node metastasis exhibited markedly higher SOX9 intensity and expression scores." (PMID 39907598, 2025). "Live imaging results in mice confirmed that SOX9‐KO exhibited a tumor inhibitory effect similar to that of CMD‐BHQ3‐PTL/DOX@RBCm." (PMID 39523731, 2025). "The CRCs with low SOX9 expression also tended to have more venous invasion (P = 0.069) and higher tumor stages (P = 0.068)." (PMID 40179020, 2025). "Co-culture of SOX9-knockout tumor cells with CD45+ T cells or peripheral blood mononuclear cells (PBMCs) significantly increased CD8+ T cell responses, an effect independent of NK cells." (PMID 41293317, 2025). "By comparing the expression of SOX9 normal samples in TCGA/GTEx with the corresponding tumor samples in TCGA, SOX9 was found significantly high expressed in 14 types of cancer, including GBM." (PMID 40692865, 2025). "In the univariate survival analysis, we found a significant prognostic impact of SOX9 expression, the subgroup of SOX2lowSOX9high tumors, tumor size, clinical stage, nodal status, and extracapsular spread." (PMID 39180200, 2025). "In this article we focused on the central role of SOX9 in the immune microenvironment, systematically elaborating its regulatory mechanisms and functions in tumor immune escape, inflammatory diseases and tissue damage repair." (PMID 41293317, 2025). "A threshold of 5% for the ratio of SOX9-positive tumor cells to total tumor cells was set, with samples exceeding this threshold considered SOX9-positive and those below it considered negative." (PMID 40428248, 2025). "As a proof of concept, we used the GMT marker Sox9, since its inhibition delays tumor growth in vivo." (PMID 41223283, 2025). "We identified a positive correlation between SOX9 expression and intensity scores and several key prognostic factors, including tumor size and differentiation, vascular and perineural invasion, and the presence of lymph node and distant metastasis." (PMID 39907598, 2025).
tumor (continued). "Despite heterogeneity in tumor mass within each group, substantial growth differences occurred when Crabp1, Mif, and Sox9 were targeted, highlighting their role in tumor growth." (PMID 41223283, 2025). "Biallelic inactivation of both Apc and Sox9 in mouse colon epithelium results in more aggressive tumor features than Apc inactivation alone." (PMID 40179020, 2025). "Given the established link between tumor stemness and drug resistance, we analyzed SOX9 expression in paired TMZ-sensitive and TMZ-resistant GBM cell pairs." (PMID 40843352, 2025). "Up-regulated SOX9 expression plays a role in acquiring stem cell phenotypes by cancer precursor cells and in initiating cancer-associated EMT process during tumor progression." (PMID 40141294, 2025). "This study highlights the effectiveness of the pH‐responsive biomimetic nanoparticle system CMD‐BHQ3‐PTL/DOX@RBCm in delivering PTL to tumor sites, with SOX9 and its upstream Hippo/YAP1 pathway playing a critical role in the underlying mechanism." (PMID 39523731, 2025). "In contrast, Paneth cell markers, including defensin alpha 1 (DEFA1), lysozyme (LYZ), and SOX9, were upregulated in tumor tissue." (PMID 41303610, 2025). "IHC staining and bioinformatics analysis revealed significantly higher expression of PRMT7 and SOX9 in NSCLC tissues than in non-tumor tissues." (PMID 41428171, 2025). "In summary, these findings collectively suggest that OIP5-AS1 fosters GIST cell proliferation and invasion by suppressing miR-145 and up-regulating SOX9, ultimately contributing to drug resistance and tumor progression in GIST." (PMID 40548429, 2025). "SOX9 helps tumor cells maintain a stem-like state and evade innate immunity by remaining dormant for extended periods." (PMID 39889187, 2025). "SOX9 expression level has been shown to correlate with drug resistance and malignant potential of tumor cells." (PMID 40141294, 2025). "Equal numbers of luciferase-labelled U87 cells transduced with control shRNA (shNC), shUSP18 or shUSP18 + SOX9 were intracranially injected into 6-week-old nude mice, and intracranial tumour growth was monitored using bioluminescent imaging." (PMID 40374599, 2025). "The role of SOX9 in colon tumorigenesis is likely context dependent, with both the tumor’s origin and overall genotypic and epigenetic status influencing SOX9 tumor suppressor function." (PMID 40179020, 2025). "HOXB6 correlated with BMI1 and SOX9 expression levels and previous studies have shown that SOX9 enhances tumor progression through BMI1 binding and p21 down-regulation which induces cell proliferation and evasion of apoptosis and senescence." (PMID 40619489, 2025). "One of the manifestations of oncogenic properties of SOX9 in cancer is the increase in tumor resistance to chemotherapy agents, in particular, to gemcitabine." (PMID 40141294, 2025). "SOX9, a member of this family, plays an important role in tumor progression, cartilage formation, and stem cell development." (PMID 41293317, 2025). "Multiomics analysis of an epithelial-enriched tumor enables the discovery of SOX9-enriched stem-like cells." (PMID 41031891, 2025). "SOX9-positive cells were quantified at a 400× magnification (0.0484 mm2), and SOX9 expression was determined based on the proportion of SOX9-positive tumor cells." (PMID 40428248, 2025). "Maintaining precise control over SOX9 protein levels is crucial, as even minor increases can significantly impact tumor initiation and progression." (PMID 40240356, 2025). "A CLDN7 knockout mice model and colorectal cell lines showed significant tumor growth, tumor cell migration, and inhibition in apoptosis via the SOX-9-mediated Wnt/β-catenin signaling pathway." (PMID 38731853, 2024). "In gastric cancer, the SOX9 expression was associated with collagen type X alpha 1 (COL10A1) to promote migration and invasion of tumor cells." (PMID 38275880, 2024).
tumor (continued). "In vitro findings reveal that silencing SOX2 enhances tumor radioresistance, while SOX9 silencing enhances radiosensitivity." (PMID 38275880, 2024). "Tumor cells in both small round/spindle cell and cartilage areas showed positive staining for SOX9, while almost only small round/spindle cell area showed positive staining for NKX3.1." (PMID 39165647, 2024). "Remarkably, a similar pattern was also depicted in metastatic lesions, which showed an increased level of SOX9 abundance with respect to the primary tumor." (PMID 38503727, 2024). "Among these factors, tumor stage, liver metastasis, surgical margin and SOX9&TCF7L2 staining (double‐high versus double‐low subgroup, HR = 2.23, 95% CI 1.10‐4.53, p = 0.026) remained significantly associated with OS in the multivariable analysis." (PMID 39492805, 2024). "Differences in the spatial expression pattern between SOX2 and SOX9 at protein levels were assessed in two distinct areas of the tumor tissue: the invasion front and the tumor core." (PMID 38275880, 2024). "A greater number of LNCaP-SOX9 cells migrated through Matrigel-coated filters compared to uninduced and parental cells, indicating that SOX9 expression enhances tumor invasion." (PMID 39459070, 2024). "To investigate the mechanisms orchestrating cancer stemness and tumour development, we analysed the transcriptional differences between differentiated (Krt20+Apoc2+Fabp2+) and stem (Lgr5+Cd44+Sox9+) cancer cells within tumours." (PMID 38658753, 2024). "SOX2 protein expression was found exclusively in the tumor cell nuclei, whereas SOX9 was expressed not only in the tumor cells but also in some parts of the tumor stroma." (PMID 38275880, 2024). "Comparing SOX9 expression between stromal cells and tumor cells a similar H-score for both compartments in tumor samples were revealed." (PMID 38275880, 2024). "Inhibin subunit beta A (INHBA) and SRY-box transcription factor 9 (SOX9) are known to influence cell differentiation and have been reported to increase tumor aggressiveness in NSCLC through induction of epithelial-mesenchymal transition (EMT)." (PMID 38674080, 2024). "The link between SOX9, expressed in tumor cells, and the CSF-1R, expressed by TAMs and particularly by the M2-like subset, is mediated by LIF/LIFR signaling." (PMID 39457693, 2024). "In situ proximity ligation assays (PLAs) conducted in HEK-293A cells and various tumor cells confirmed YAP-SOX9 interaction in both the cytoplasm and the nucleus, whereas the depletion of SOX9 in Huh-7 cells completely diminished the fluorescence signal." (PMID 38653754, 2024). "SOX9 protein expression was higher in the invasive front compared to very few SOX9 positive cells in the tumor core." (PMID 38275880, 2024). "The cell lines with high SOX9 expression exhibited a higher number of tumor sphere formation as compared to controls." (PMID 38275880, 2024). "In fact, this alteration completely halted bone lesion development, indicting a pivotal role of SOX9 in mediating PCa tumor metastasis driven by AR-V7." (PMID 38687617, 2024). "Due to the differences in size of tumor samples, four areas of equal size per tumor were selected and were evaluated for SOX9 protein staining." (PMID 38275880, 2024). "Results of whole‐genome CRISPR screening from the DepMap project demonstrated strong tumor dependency of CDK7 in all tested GBC lines disregarding the expression levels of SOX9 and TCF7L2." (PMID 39492805, 2024). "In summary, a significant number of stromal cells in the TME were SOX9 positive, with intensity and proportion similar to tumor cells." (PMID 38275880, 2024). "SOX10, a transcription factor expressed by migratory NC cells, has been shown to be highly expressed by melanoma cells and required for tumor formation, while SOX9, a NC specifier, rather regulates tumor invasion." (PMID 38282579, 2024).